MMP2 (matrix metallopeptidase 2)
Diseases named in the same sentence as MMP2 in open-access papers (continued):
Sharing a sentence is not in itself a finding about the gene and the disease.
oral cancer (75 papers, 2010 to 2025). "Similar results were observed in the context of oral cancer; Galectin-1 regulated matrix metalloproteinase (MMP)-2 and MMP-9 expression, causing tumor invasion." (PMID 37433225, 2023). "In oral cancer, previous studies have verified that patients with MMP-2 −735 CC genotype present increased risk for developing oral squamous cell carcinoma when compared to those with CT or TT genotype." (PMID 27194818, 2016). "Furthermore, MMP-2 is associated with metastasis in oral cancer, nasopharyngeal carcinoma, eye cancer, and brain cancer." (PMID 32397656, 2020). "The other possible mechanism that modulates the transcriptional activity of MMP-2 gene is due to the Ras mutation, which is found in approximately 50% of all oral cancer patients in South Asian population, majority of which are thought to be associated with the habit of chewing tobacco." (PMID 24591757, 2014). "Reduces migration, invasion and metastasis;the activities and protein levels of the MMP-2 and urokinase-type plasminogen activator (u-PA) was inhibited; chemopreventive agent against oral cancer metastases." (PMID 39518052, 2024). "Earlier studies have shown that extracts from Dioscorea nipponica Makino (DNE) suppress the activity of the matrix metalloproteinase-2 (MMP-2) enzyme, as well as its RNA and protein levels, in oral cancer cell lines Ca9-22 and Cal-27." (PMID 38374934, 2024). "In line with our findings, previous studies on oral cancer cells have also reported the inhibitory effects of CTX on crucial modulators associated with cell migration and invasion, including MMP-2, MMP-9, and COL1A1." (PMID 39114354, 2024). "Oral cancer cell migration and invasion can be encouraged by elevated MMP-2 and MMP-9 expression and activity." (PMID 38068849, 2023). "Similar results were obtained in a chronic stress model of oral cancer in mice, where cortisol and catecholamines augmented MMP-2 and VEGF expression in the tumor tissue." (PMID 36213817, 2022). "Among these associations, MMP-2 rs243865 was connected with LC risk and MMP-9 rs3918242 with BC, HCC, LC, and oral cancer risk." (PMID 35574300, 2022). "Anthocyanins from a species of black rice can suppress the in vitro migration and invasion of human oral cancer CAL 27 by reducing MMP-2, MMP-9, and NF-kB p65 expression through the suppression of the PI3K/Akt pathway and inhibition of NF-kB expression." (PMID 34206588, 2021). "In conclusion, the present study clearly demonstrates that luteolin-7-O-glucoside can significantly reduce the oral cancer metastasis by mitigating p38-induced increased expression of MMP-2." (PMID 32224968, 2020). "In agreement with the inhibitory effect on MMP-9 activity, we further found that low concentration of WFA (>95% viability) exhibits inhibitory effects on MMP-2 activity in oral cancer Ca9-22 cells." (PMID 32429564, 2020). "This is the first study to demonstrate the luteolin-7-O-glucoside inhibits cell migration and invasion by regulating MMP-2 expression and extracellular signal-regulated kinase pathway in human oral cancer cell." (PMID 32224968, 2020). "Using a p38 inhibitor, SB203580, we confirmed that luteolin-7-O-glucoside reduces oral cancer cell migration by altering p38-induced activation of MMP-2." (PMID 32224968, 2020). "As expected, our results indicated that sesamin can reduce MMP-2 protein expression and further inhibit the migration and invasion ability of three oral cancer cell lines." (PMID 32397656, 2020). "Increased MMP-2 and MMP-9 expression in human oral cancer tissues was significantly associated with T-stage and lymph node metastasis." (PMID 32102512, 2020). "The release of MMP-2 and MMP-9 is increased in various types of cancers including oral cancer and their increased levels are associated with poor prognosis." (PMID 32922544, 2020).
oral cancer (continued). "Taken together, all these findings clearly indicate that luteolin-7-O-glucoside-induced inhibition of oral cancer cell metastasis is mediated by the combined action of p38 and MMP-2." (PMID 32224968, 2020). "Various studies had shown the anti-metastatic effects of certain agent on NPC or oral cancers through the downregulation of MMP-2 or MMP-9 via the MAPK signaling pathways." (PMID 31850235, 2019). "Previous studies indicated that the MAPK pathways were involved in the regulation of MMP-2 expression on oral cancer cells." (PMID 31850235, 2019). "In the present study, we demonstrated that berberine suppressed the migration of KB oral cancer cells through the downregulation of both MMP-2 and MMP-9." (PMID 25634589, 2015). "In contrast, in the KB oral cancer cells that were treated with berberine, the expression of MMP-2 and MMP-3 was regulated by the p38 MAPK signaling pathway." (PMID 25634589, 2015). "Increased MMP-2 secretion from oral cancer cells significantly correlated with increased cell invasion." (PMID 24931737, 2014). "Our results showed that Selaginellatamariscina halted oral cancer cell migration through the down-regulation of MMP-2 and MMP-9 expression and by decreasing DNA-binding activity to promoter elements." (PMID 23799155, 2013). "Consistently, the CTXIII mediated MMP2/9 to inhibit the migration of oral cancer cells in current study." (PMID 23710144, 2013). "Caffeic acid phenethyl ester inhibits oral cancer cell metastasis by regulating the MMP-2 and MAPK pathways." (PMID 24278338, 2013). "The results of this study show that Selaginellatamariscina reduced oral cancer migration and invasion by inhibiting MMP-2 and MMP-9 gene expression, and enzyme activity." (PMID 23799155, 2013). "Previous studies investigated the clinical significance of MMP-2 in different races with oral cancer." (PMID 23320037, 2012). "Results also indicated that the anti-invasive activity of CAPE is partly mediated by the regulation of MMP-2 expression and activity, which reduces the ability of oral cancer cells to degrade components of the extracellular matrix." (PMID 23320037, 2012). "In conclusion, the result of our study suggested that CAPE partly exerts its antimetastatic effects on oral cancer cells by regulating MMP-2 expression through the inhibition of FAK and MAPK activation." (PMID 23320037, 2012). "The phytochemical study on Quercus infectoria identified several gallotannins, including 6‐O‐digalloyl‐1,2,3,4‐tetra‐O‐galloyl‐β‐D‐glucose, with a strong binding affinity against oral cancer targets such as MMP‐2, NF‐κB p65, and RhoA, showing binding energies up to −10.6 kcal/mol (AutoDock v4.2.6)." (PMID 40933552, 2025). "In a model of oral cancer, resveratrol suppressed the metastasis and invasion of H-357 cells by inhibiting the activity of MMP-2 and MMP-9 and numerous inflammation mediators, e.g., NF-κB, COX-2, inducible nitric oxide synthase (iNOS), TLR4, TNF-α, interleukin-1 β (IL-1 β), and interleukin-6 (IL-6)." (PMID 39335164, 2024). "Moreover, CAPE exerts its antimetastatic effects in oral cancer by downregulating the expression of matrix metalloproteinase-2 (MMP-2) following the failure of focal adhesion kinase (FAK) and MAPK signaling activation." (PMID 37372967, 2023). "Furthermore, the depletion of CRT from oral cancer cells resulted in the decreased activity of matrix metalloproteinase-2 (MMP-2) and MMP-9, possibly due to the downregulation of the FAK-ERK-MMP-2/MMP-9 signaling pathway." (PMID 37979915, 2023). "In addition, we investigated the association between MMP-2 expression and the MAPK pathway in sesamin-treated oral cancer cells." (PMID 32397656, 2020). "Accordingly, WFA inhibits migration of oral cancer cells by inactivating MMP-2 and MMP-9." (PMID 32429564, 2020).
oral cancer (continued). "Given the significant effect of SB203580 and luteolin-7-O-glucoside co-treatment on cell motility, we performed trans-well migration assay to finally prove the involvement of p38 pathway and MMP-2 in mediating luteolin-7-O-glucoside-induced reduction in oral cancer cell migration." (PMID 32224968, 2020). "Additionally, quercetin suppressed cell viability, migration, and invasion by regulating miR-16/HOXA10, which inhibits the expression of MMP-2 and 9 in oral cancer cells." (PMID 32050534, 2020). "For example, MMP2, 7, and 9 are overexpressed in oral carcinoma tissue." (PMID 25424420, 2014). "Our results indicated that SHP2 increases MMP-2 secretion in oral cancer cells." (PMID 24931737, 2014). "Quercetin (50 μM) has also been found to reduce the protein levels of MMP-2 and MMP-9 in oral cancers." (PMID 39335164, 2024). "In support of our results, P. gingivalis LPS has been shown to upregulate the expression of MMP2 and MMP9 in oral cancer cells." (PMID 36552854, 2022). "In oral cancer, quercetin increases miR-16 expression levels, which in turn targets MMP-9, MMP-2 and HOXA10, so quercetin can prevent cell proliferation, migration, and survival in oral cancer." (PMID 35971151, 2022). "Gelatinases, including MMP-2 and MMP-9, are another subfamily of MMPs that is well-established as important markers in the malignant progression of oral cancer." (PMID 36330492, 2022). "Research on the oral cancer cells and tissue of OSCC patients suggests that MMP-2 and MMP-9 are frequently seen to promote infiltrative growth and bone resorption." (PMID 36011038, 2022). "In oral cancer cells, treatment with GDF-11 stimulates cell migration and induced expressions of MMP2 and MMP9." (PMID 35705978, 2022). "miR-365 was detected among these oral cancers, and some cells also expressed NKX2.1 and MMP-2, which correlated with miR-365 levels." (PMID 34204617, 2021). "By reducing NF-κB, MMP-2 and MMP-9 expression, anthocyanins can inhibit the metastasis of pancreatic and oral cancer." (PMID 34206588, 2021). "Published reports show that MMP2 and MMP9 are upregulated in OSCCs, where they aid in the invasiveness of oral cancer cells, and silencing DSPP decreases oral cancer cell invasion." (PMID 32630820, 2020). "Mechanically, this safe treatment of WFA inhibits MMP-2 and MMP-9 activities and induces antioxidant gene expression as well as MAPK activation in oral cancer cells." (PMID 32429564, 2020). "This study found that after treatment with SnO2 NP, both MMP-2 and MMP-9 protein and mRNA expressions in oral cancer cells were down-regulated by varying degrees." (PMID 32766221, 2020). "In a clinical setting, the expression of MMP2 and MMP9 has appeared to be closely related to metastasis in oral cancer." (PMID 25330185, 2014). "Our previous study also showed that silibinin inhibits the invasion of oral cancer cells by suppressing the activation of ERK1/2 and MMP-2 expression." (PMID 25184134, 2014). "Silibinin inhibits the invasion of oral cancer cells by suppressing the activation of ERK1/2 and the MMP-2 expression." (PMID 24278338, 2013). "Elevated MMP-2 and MMP-9 expression have been observed in invasive and metastatic cases of human oral cancer." (PMID 23799155, 2013). "In conclusion, CTXIII has antiproliferative and -migrating effects on oral cancer cells involving the p38-MAPK and MMP-2/-9 pathways." (PMID 23710144, 2013).
oral cancer (continued). "Consequently, this results in decreased levels of MMP-2, MMP-9, and uPAR proteins, curtailing the migratory and invasive capabilities of these oral cancer cells." (PMID 38374934, 2024). "Thus, when 4-carbomethoxyl-10-epigyrosanoldie E inhibits RhoA expression, this leads to a decrease in MMP-2 and MMP-9 levels, impacting the migration and invasion of Cal-27 and Ca9-22 oral cancer cells." (PMID 38374934, 2024). "In addition, due to the critical roles of MMPs in tumor cell invasion and metastasis, MMPs such as MMP2 and MMP9 have been identified as prognostic factors for many types of cancer, such as head and neck squamous cell carcinomas (HNSCCs) and oral cancers." (PMID 35203529, 2022). "A related study on a cohort of 145 oral cancer patients exhibited high levels of MMP2 in severe patients when compared to non-severe oral cancer patients." (PMID 34490084, 2021). "Therefore, a low concentration of WFA has the potential to inhibit the MMP-2 and MMP-9 activities in order to inhibit migration or metastasis of oral cancer cells." (PMID 32429564, 2020). "The present results show that that sesamin inhibited the motility, migration, and invasion of and downregulated MMP-2 in oral cancer cells without exerting any cytotoxic effects." (PMID 32397656, 2020). "MMP-2 and MMP-9, which are secreted by invasive cancer cells, play important roles in cancer cell invasion and metastasis because tumor cells must cross the type IV collagen-rich basement of vessel walls to spread to other sites during oral cancer metastasis." (PMID 30143678, 2018). "In addition, the expression of both MMP-2 and MMP-9 was significantly decreased in the KB oral cancer cells that had been co-stimulated with berberine and the p38 MAPK-specific chemical inhibitor compared to those that had been treated with berberine only." (PMID 25634589, 2015). "Although the p38-MAPK and MMP-2/-9 were mediated in CTXIII-induced inhibition of migration in oral cancer cells, the phosphorylation of ERK was not involved in current study." (PMID 23710144, 2013). "For example, the levels of MMP-2 and MMP-9 proteins were related to invasion of oral cancer." (PMID 23710144, 2013). "This study demonstrates the roles of p38-MAPK and MMP-2/-9 pathways involved in the inhibition effect of proliferation and migration under CTXIII treatment in human oral cancer cells, and it may provide a potential oral cancer therapy." (PMID 23710144, 2013). "Therefore, overexpression of MMP-2 and MMP-9 may serve as indicators of metastatic phenotype, suggesting that monitoring changes in MMP expression following treatment could be a valuable marker for assessing treatment outcomes in patients with oral cancer." (PMID 39408625, 2024). "However, treatment of the oral cancer cells with ERK inhibitor resulted in no significant changes in MMP-2 secretion (data not shown), indicating that signaling pathways other than ERK1/2 might be involved in SHP2-mediated MMP-2 secretion." (PMID 24931737, 2014).
myopia (73 papers, 2011 to 2026). "Fourth, changes in Zc3h11a expression were found to cause changes in the myopia-related genes Tgfβ1, Mmp2, and Il6." (PMID 40864167, 2025). "In the mouse model of simple myopia, scleral NLRP3 inflammasome activation is linked with MMP-2 upregulation, scleral matrix remodeling, and myopia progression." (PMID 40909333, 2025). "A decreased VEGF concentration and increased MMP-2 concentration in the aqueous humor factor have potential associations with the development of high myopia." (PMID 39086954, 2024). "Mmp2 overexpression via subtenon-delivered adeno-associated virus (AAV) led to myopia in WT mice, while RNA interference–mediated knockdown of Mmp2 attenuated FDM development." (PMID 38635876, 2024). "Increases in the expression and activity of MMP-2 are associated with increased scleral collagen degradation and scleral thinning in both human and animal myopia." (PMID 36652495, 2023). "These agents then activate MMP-2 expression in the retina, followed by the sclera, leading to cleavage of collagen, causing scleral remodeling as well as the onset of myopia." (PMID 37849748, 2023). "Scleral remodeling can lead to exaggerated eye growth, causing myopia, for which MMP-2 has a major role in this process." (PMID 36289864, 2022). "We also investigated the molecular mechanisms underlying the attenuation of myopia development using RNA-seq and found that Col1a1 and Mmp2 expression levels were upregulated by brimonidine treatment." (PMID 34256866, 2021). "Among the MMP isoforms, it has been consistently reported that elevated MMP2 activity is associated with myopia in animal studies, although less is known regarding their inhibitory regulator TIMP2 and related molecules such as TGF-β." (PMID 34698138, 2021). "Among MMPs, MMP-2 (72 kDa, gelatinase A) is a significant factor reported to be associated with myopia." (PMID 32596291, 2020). "In contrast to MMP-2, which has been well portrayed in scleral remodeling and thinning during experimental myopia studies, IL-6 is seldom implicated in myopia." (PMID 30837544, 2019). "This network was composed primarily of genes involved in immune-mediated ECM remodeling, and included connections with many intermediate genes that have been strongly linked to myopia in previous targeted studies (e.g. MMP2, TGFB1, TGFB2, FGF2, INS, and IGF2)." (PMID 28852117, 2017). "Additional studies for mutation screening are necessary to evaluate the role of the MMP2 gene in the genetic susceptibility to high myopia." (PMID 23378725, 2013). "MMP2 Variants detected in 200 high myopia and 200 control subjects by direct sequencing of all the exons *Minor allele/major allele." (PMID 23378725, 2013). "Differential MMP2 expression has been implicated in scleral remodeling in experimental myopia studies in tree shrews and chicks." (PMID 23378725, 2013). "Riboflavin/UVA SXL could slow myopia progression and thicken the cross-linked sclera in guinea pigs, which might be related to the downregulation of MMP-2 and MT1-MMP expression during the scleral remodeling process." (PMID 36652495, 2023). "Inflammatory cytokines IL-6 and TNF-α in the retina may serve as triggers to initiate MMP-2 activity in the retina, followed by sclera, causing progressive scleral remodeling and myopia." (PMID 36031679, 2022). "In addition, the proteins encoded by Col1a1 and Mmp2 are involved in angiogenesis and the myopia pathway (among other activities) in mice and guinea pigs." (PMID 34256866, 2021). "Moreover, an injection of Adeno-associated virus 8 packaging with shRNA to MMP-2 suppressed the form of deprivation-induced increases in the latter’s expression and in myopia development." (PMID 33291388, 2020). "Therefore, it is impossible to confirm or deny the susceptibility of the MMP2 gene with high myopia based on the current evidence, especially because of our limited understanding of complex diseases." (PMID 23378725, 2013).